SIRT1 (sirtuin 1)
Diseases named in the same sentence as SIRT1 in open-access papers (continued):
Sharing a sentence is not in itself a finding about the gene and the disease.
metabolic disorders (continued). "This review focuses on the role of SIRT1 in endocrine and metabolic diseases." (PMID 36632457, 2023). "Importantly, SIRT1 have been widely studied in clinical practice and gradually become key molecules in the treatment of endocrine and metabolic diseases and aging related diseases." (PMID 36632457, 2023). "Ongoing work in sirtuin-targeted drug discovery may ultimately lead to the consideration of SIRT1 inhibitors as therapeutic alternatives to or amplifiers of PPARα agonists (e.g., fibrates) for metabolic disorders." (PMID 35419389, 2022). "Moreover, resveratrol was reported to improve mitochondrial function and protect against metabolic disease by activating SIRT1 and PGC-1α." (PMID 35681729, 2022). "Stimulation of SIRT1 by melatonin in DM may explain the pleiotropic functions of melatonin in treating metabolic disorders." (PMID 35962432, 2022). "Initially, Sirt1 research focused on its role in prolonging the life span of lower organisms, but recent studies have shown that Sirt1 activity can affect a variety of proteins involved in metabolic diseases." (PMID 33159388, 2021). "A plethora of recent studies have confirmed that SIRT1 indeed inhibited the NF-κB signaling, and the activation of SIRT1 could alleviate a multitude of NF-κB-driven inflammatory and metabolic disorders." (PMID 34071594, 2021). "Among them, SIRT1 is involved in inflammation and metabolic diseases." (PMID 33510583, 2021). "As a member of NAD+-dependent deacylase, SIRT1 has been reported to correlate with inflammatory response and metabolic disorders in various tissues and organs, involved in multiple cellular signaling pathways that contribute to cytoprotective effects and metabolic regulation." (PMID 33867828, 2021). "SIRT1 plays a vital role in the pathology, progression, and treatment of several diseases, including neurological disorders such as Alzheimer's disease, cardiovascular disease, metabolic disease, and aging-related disease." (PMID 33546744, 2021). "Therefore, AMPK and SIRT1 represent as potential targets for the development of therapies to prevent and reduce the incidence of metabolic disease complications and development." (PMID 34656137, 2021). "Further investigation to verify whether SIRT1 may act as a potential target for the treatment of metabolic disorders or help monitoring the effect of new drugs to improve the energy metabolism is warranted." (PMID 33202604, 2020). "It remains to be elucidated whether other characteristics of cellular senescence, such as macromolecular (protein and lipid) damage and metabolic disorders are involved in SIRT1-mediated VSMC function." (PMID 33117155, 2020). "Sirtuin 1 (SIRT1) regulates protein deacetylation, participates in protein transcription and translation, regulates cell proliferation, oxidative stress, and metabolism, and plays an important role in metabolic diseases, tumors, and cardiac function." (PMID 32425778, 2020). "Despite the critical roles of SIRT1 in metabolic regulation, there have been no studies suggesting that the beneficial effects of probiotics on risk factors for metabolic disorders are mediated by the positive modulation of SIRT1/PGC-1α pathway." (PMID 32040532, 2020). "The results of this study support previous findings that exercise regulates tissue specific changes of SIRT1 and other sirtuins expression and activity in many tissues including skeletal muscle, brain, adipose tissue, and heart, thereby preventing metabolic diseases or aging-related disorders." (PMID 30988688, 2019). "Sirtuin-1 (SIRT1), a protein deacetylase, is directly implicated in the modulation of inflammatory response and plays an important role in various metabolic and pathophysiological processes, such as inflammation, endothelial function and metabolic disorders." (PMID 31844680, 2019).
metabolic disorders (continued). "In addition to disrupting inflammation, recent studies demonstrated that SIRT1 inhibits NF-κB to suppress various metabolic diseases, including glucose homeostasis and cardiovascular disease." (PMID 31299012, 2019). "On the basis of previous work and this study, SIRT1 may acts as a protector from PM-related consequences, including cardiopulmonary and metabolic disease, by interfering in NF-κB inflammation via SREBP1-PIR signaling pathway." (PMID 31299012, 2019). "As these metabolic disorders are important risk factors of CKD, the improvements in systemic glucose and lipid metabolism by SIRT1 may also contribute to the attenuated kidney disorders due to maternal HFD in the offspring." (PMID 30641941, 2019). "Moreover, Sirt1 protects against metabolic disease by activating Sirt1 itself and the α subunit of peroxisome proliferators-activated receptor-γ coactivator-1 (PGC-1α) and ameliorates spatial learning memory impairment induced by Aβ1–42." (PMID 29439655, 2018). "Sirt1 is a NAD+-dependent deacetylase that mediates the effects of caloric restriction, stimulates AMPK, and improves mitochondrial function, and its dysfunction is associated with metabolic diseases." (PMID 28640832, 2017). "In addition, resveratrol improves mitochondrial function and protects against metabolic disease by activating SIRT1 and PGC-1α." (PMID 27213310, 2016). "Since Sirt1 protects against metabolic disorders by facilitating FA oxidation, we hypothesized that β-lap-mediated activation of Sirt1 activity can prevent lipotoxic cardiomyopathy." (PMID 24614171, 2014). "PPARγ and the PPARγ coactivator (PGC)-1α, which play key roles in various metabolic disorders, are also known to be targeted by SIRT1, but the effects of telmisartan on SIRT1- and PPARγ-signaling remain unclear." (PMID 23137106, 2012). "Despite extensivestudies on SIRT1 function and its beneficial metabolic effects, how theexpression of SIRT1 is regulated under normal conditions and how SIRT1 levelsare decreased in metabolic disease states remain unclear." (PMID 20689156, 2010). "Also, it will be important to understand how the FXR/SIRT1 regulatory network isdysregulated in metabolic disease states which likely involves altered cellularkinase signaling pathways that post-transcriptionally affect SIRT1 and FXRlevels and activities." (PMID 20689156, 2010). "Given the impact of SIRT1 on PPARγ activityand because PPARγ activity helps determine age-related insulinresistance, SIRT1 may have animportant role in metabolic diseases and link the effects of food consumptionto body fat mass and diseases of aging." (PMID 18317516, 2007). "By targeting mTOR, SIRT1 and other pivotal molecules, immune metabolic dual regulatory natural products can synchronously regulate immune response and metabolic activities, and block the vicious cycle of immune activation, metabolic disorder and vascular remodeling." (PMID 41585867, 2025). "Estradiol has been shown to increase the expression and activity of SIRT1 in numerous tissues, including the heart and blood vessels, while the absence of estradiol reduced SIRT1 activity, which was associated with metabolic disorders and promoted age-related diseases." (PMID 41011644, 2025). "Given the ability of SIRT1 to regulate common pathways leading to both AS and metabolic disease, it is suggested that the inhibition of AS may be achieved through similar mechanisms employed in metabolic disease prevention, partly attributed to SIRT1." (PMID 37298289, 2023). "However, TRF/E may contribute to the prevention of metabolic diseases via modulation of the Clock–Bmal1 pathway, synchronizing hormonal signals, regulating the Sirt1 pathway, inhibiting mTOR signaling, and modulating gut-microbiome-related nutrient-sensors." (PMID 36678130, 2023).
metabolic disorders (continued). "Obviously, further studies testing whether SIRT1 could work as a potential target for the therapeutic approaches of metabolic disorders, or could help monitor the effect of novel medications to ameliorate the clinical conditions of patients affected by AN, are needed with longitudinal design." (PMID 37373917, 2023). "Finally, we propose future research directions between SIRT1 and endocrine and metabolic diseases." (PMID 36632457, 2023). "As the role of SIRT1-mediated autophagy in metabolic disorders have been increasingly highlighted, clinical and animal studies have been conducted to validate the use potential SIRT1 modulator as a therapeutic intervention for endocrine disorders by targeting SIRT1-autophagy axis." (PMID 35909524, 2022). "SIRT1 and SIRT6 have beneficial effects against metabolic diseases, but we demonstrate that Sirt7 knockout mice are protected from high-fat-diet–induced obesity, glucose intolerance, and fatty liver, suggesting that SIRT7 deficiency plays a beneficial role in metabolic disorders." (PMID 36012298, 2022). "Marton and his colleagues showed that in metabolic disorders caused by aging, exercise could not prevent the reduction of SIRT1 in the cerebellum, which is contrary to our results." (PMID 35236328, 2022). "However, whether and to what extent NAD+ metabolic disorder can affect Sirt1/ NF-κB P65/FN remains to be further studied for better understanding of the determinants of Sirt1 beneficial effects in DN." (PMID 35408818, 2022). "The findings suggest that Sirt1 plays an important protective role against WD induced large artery stiffening and may be a therapeutic target in the management of arterial stiffening in a metabolic disease population." (PMID 35561022, 2022). "The decrease of SIRT1 expression and activity is a major characteristic of metabolic diseases, and its mechanism partly explains the influence of a high-fat diet on metabolic syndrome, obese diabetes, cardiovascular disease, and other related metabolic diseases." (PMID 34616289, 2021). "So it is clear that the AMPK/SIRT1/PGC-1α network is a critical energy-sensing signaling pathway and that AMPK activation will induce the concurrent deacetylation and phosphorylation of its downstream targets and relieve the susceptibility to IR-associated metabolic disorders." (PMID 34326919, 2021). "However, studies investigating the association of genetic variants on SIRT1 and metabolic disorders in HIV-infected individuals under HAART have not been found." (PMID 32106282, 2020). "Accumulated evidence show that, under metabolic disorder conditions, intracellular NAD+ levels decreased in metabolic tissues, including the liver, adipose tissue, skeletal muscle, which is associated with decreased activation of SIRT1, a NAD+-dependent deacetylase." (PMID 32040532, 2020). "Thus, increasing the SIRT1 level and decreasing the fetuin-A level could be promising new therapeutic approaches for treating metabolic disorders such as T2DM." (PMID 29803203, 2019). "In addition, after MF or EX treatment, the elevation in AMPKα and SIRT1 expression indicated that AMPKα-SIRT1 pathway might participate in the improvement of metabolic disorder due to MF or EX treatment." (PMID 31526389, 2019). "As mitochondrial dysfunction caused by metabolic disorders is the main origin of ROS generation in DCM, SOD2 has an extremely pivotal role in regulating ROS homeostasis after being deacetylated from Ac-SOD2 by the effect of several kinds of sirtuins, in which SIRT1 plays a crucial role." (PMID 31210844, 2019). "These possibilities should be tested in animal models and could form the basis for novel therapeutic approaches to metabolic disease that employ SIRT1 modulators in combination with several thyromimetics that exhibit improved safety profiles relative to native thyroid hormones." (PMID 23922917, 2013).
metabolic disorders (continued). "The SIRT1/AMPK pathway is well known for its ability to regulate inflammatory responses and metabolic disorders, especially in relation to an alcoholic liver injury." (PMID 40219012, 2025). "For example, a study demonstrated that remodeling of the ECM in adipose and muscle tissue plays a pivotal role in metabolic disease development, identifying genes such as TCF7L2, ADIPOQ, CD36, PPARG, IL6, SIRT1, and COL5A1 as key regulators of inflammation." (PMID 41303617, 2025). "Activation of the AMPK/SIRT1/PGC-1α axis through combined bioactive supplementation and exercise represents a promising framework for personalized metabolic disease management." (PMID 41573560, 2025). "Natural compounds show great promise for treating various diseases by precisely adjusting the AMPK/SIRT1/PGC‐1α pathway, providing new approaches for metabolic disorders, brain diseases, and organ damage." (PMID 41268687, 2025). "Resveratrol, a known SIRT1 agonist, has been proven to improve mitochondrial function by stimulating SIRT1 expression and maintaining PGC-1α activity in metabolic diseases, COPD." (PMID 39830343, 2024). "Stimulation of SIRT1 and AMPK results in the activation of PPARγ coactivator 1 α, placing mitochondria at the epicenter of targets for polyphenols in CVD and metabolic disorders." (PMID 39458640, 2024). "As demonstrated for other key metabolic regulators, such as AMPK (which is also an activator of SIRT1 and HSR), in people with metabolic diseases, the induction of this protein is delayed after the metabolic challenge." (PMID 39458523, 2024). "SIRT1, a highly conserved NAD+-dependent deacetylase, is one member of the SIRT family of class III HDACs involved in the development of endocrine and metabolic diseases." (PMID 37501791, 2023). "SIRT1, SIRT6, and SIRT7 are nuclear proteins, and SIRT1 and SIRT6 exert beneficial effects against metabolic diseases." (PMID 36429037, 2022). "Resveratrol also affects mitochondrial metabolism and homeostasis, and it prolongs the lifespan by activating SIRT1 and peroxisome proliferator-activated receptor-γ coactivator-1α (PGC1-α) in metabolic disease." (PMID 35517847, 2022). "Taken together, CR can improve metabolic disorders induced by HFD through activating thermogenesis and reducing inflammation in sWAT and hepatic tissue by AMPK/SIRT1 signaling pathway." (PMID 35721807, 2022). "Previous studies have reported the regulation of Lkb1 at protein levels, such as SIRT1 and SIRT2 functioned as the upstream regulators for Lkb1/AMPK signaling and played essential roles in the metabolic diseases." (PMID 35986288, 2022). "Divided into 4 classes, SIRT1 and SIRT3 are categorized into class I, which primarily encompasses involvement in metabolic diseases and FA oxidation." (PMID 35042927, 2022). "SirT1 is a highly conserved NAD+-dependent protein deacetylase that has emerged as a critical regulator of aging and metabolic disease." (PMID 34679684, 2021). "Taken together, these results suggest that the JTXK granule ameliorates skeletal muscle IR through activation of the AMPK/SIRT1/PGC-1α signaling pathway, which offers a novel perspective of this formula to combat IR-related metabolic diseases." (PMID 34326919, 2021). "For the subsequent cardioprotective effects of Sirt1 in the presence of RSV, improving metabolic disorders is shown to be the key part." (PMID 32256959, 2020). "By contrast, germline or cell-specific overexpression of SIRT1 or SIRT6 were reported to expand lifespan and defense metabolic diseases in insulin-dependent and independent manners." (PMID 30574122, 2018). "Among them, SIRT1 belongs to class III histone/protein deacetylases, and its dysregulation has been shown to be involved in aging, metabolic diseases and inflammation." (PMID 28740165, 2017). "Sirt1 and AMPK are two key sensors of cellular metabolic status and activation of these molecules corrects a variety of metabolic disorders." (PMID 24614171, 2014).
metabolic disorders (continued). "Indeed several recent studies confirmed that SIRT1-mediated deacetylation of p65/RelA inhibited the NF-κB signaling and the activation of SIRT1 could alleviate a multitude of NF-κB-driven inflammatory and metabolic disorders." (PMID 25260046, 2014). "Our results provide fundamental information to reveal the cat SIRT1 and SIRT3 function about relationship of metabolic diseases." (PMID 24073959, 2013). "This study found that graphene-FIR therapy could activate the thermogenic program in adipose tissue, increasing the protein expression of AMPK/SIRT1/PGC-1α in adipose tissue (iWAT and BAT) and improving metabolic disorders in HFD mice." (PMID 40076847, 2025). "Similarly, resveratrol activates sirtuin 1 (SIRT1), possesses antioxidant activity, and activates AMP-activated protein kinase (AMPK), contributing to its medicinal properties against metabolic disorders." (PMID 39204080, 2024). "Moreover, inactivating the sirtuin 1 (Sirt1)/AMPK pathway has been observed in obese mice, which aggravates metabolic disorders." (PMID 34054544, 2021). "As SIRT1 is a NAD+-dependent histone deacetylase, NAD+ supplement by providing its precursors such as nicotinamide riboside (NR) and nicotinamide mononucleotide (NMN) has been proved to be beneficial in treating CVDs and metabolic diseases in animal models." (PMID 33117155, 2020). "SIRT1, an NAD+-dependent deacetylase, has important effects on metabolic diseases, including ALD." (PMID 35541657, 2018). "SIRT1 is already known related to many metabolic diseases, such as obesity, diabetes, and nonalcoholic fatty liver." (PMID 29147649, 2017). "Supporting this hypothesis, our data revealed that BCH treatment could increase NAD+/NADH ratio and SIRT1/AMPK activity and improve most metabolic disorders by HF/HFr western diet." (PMID 27874078, 2016). "Recent reports using different transgenic models have suggested that SIRT1 and AMPK might act in an orchestrated signaling network to improve metabolic disorders." (PMID 25874615, 2015). "Both SIRT1 and AMPK have been considered as attractive targets for the regulation of transcriptional networks to promote whole-body energy expenditure and treat metabolic disorders." (PMID 25874615, 2015). "SIRT1, an NAD-dependent deacetylase, has a critical role in metabolic diseases, including NAFLD." (PMID 26203862, 2015). "Sirtuin 1 (SIRT1) is an NAD+-dependent deacetylase that is activated by resveratrol and regulates the expression of genes involved in fasting response and resistance to metabolic diseases." (PMID 23922917, 2013). "SIRT1, the mammalian orthologue of yeast Sir2, is a highlyconserved NAD+-dependant protein deacetylases that has emerged as an importantregulator of aging and metabolic disease." (PMID 20375467, 2010). "SIRT1, a member of the class III sirtuin family, senses the cellular energy by rise in the NAD+/NADH ratio and stimulates fat utilization to prevent diet-induced metabolic diseases." (PMID 20976254, 2010). "Additionally, the insulin-sensitizing effects of the polyphenol, Resveratrol, through modulation of SIRT1/PGC-1α activity, have been highlighted as being beneficial in tackling aspects of metabolic disease." (PMID 21113404, 2010). "Importantly, interactions between SIRT1, peroxisome proliferator-activated receptor gamma coactivator 1 (PPARGC1A), and FOXO1/FOXO3 indicate a strong mitochondrial and antioxidant component, aligning with their roles in metabolic disease and aging." (PMID 40664894, 2025).